ACOT7 (acyl-CoA thioesterase 7)
Description:
Catalyzes the hydrolysis of acyl-CoAs into free fatty acids and coenzyme A (CoASH), regulating their respective intracellular levels. Preferentially hydrolyzes palmitoyl-CoA, but has a broad specificity acting on other fatty acyl-CoAs with chain-lengths of C8-C18. May play an important physiological function in brain.
Synonyms: BACH; hBACH; CTE-II; ACH1; ACT; LACH1; MGC1126; LACH
Tractability: PROTAC: ubiquitination databases record sites on it; its protein half-life has been measured.
Target class: Enzyme; Hydrolase
Gene: Protein-coding gene on chromosome 1 (6,264,268 to 6,393,767, reverse strand). Ensembl gene ENSG00000097021.
Subcellular location: Cytoplasm, cytosol (Isoform 4); Cytoplasm, cytosol (Isoform 6); Mitochondrion (Isoform 1); Mitochondrion (Isoform 5)
Subcellular location (Human Protein Atlas): Cytosol
Pathways (Reactome):
Metabolism: Mitochondrial Fatty Acid Beta-Oxidation
Gene Ontology:
Molecular function: fatty-acyl-CoA binding; long-chain fatty acyl-CoA binding; long-chain fatty acyl-CoA hydrolase activity; protein binding; protein homodimerization activity; fatty acyl-CoA hydrolase activity; medium-chain fatty acyl-CoA hydrolase activity; thiolester hydrolase activity
Biological process: coenzyme A biosynthetic process; long-chain fatty-acyl-CoA catabolic process; medium-chain fatty acid biosynthetic process; medium-chain fatty-acyl-CoA catabolic process; palmitic acid biosynthetic process; acyl-CoA metabolic process; fatty acid catabolic process; fatty acid metabolic process
Cellular component: cytosol; extracellular exosome; mitochondrion; cytoplasm; cell body; mitochondrial matrix; neuron projection
Genetic constraint (gnomAD): Loss-of-function variants: 11 observed, 38.87 expected, observed/expected ratio (o/e) 0.28, 90% interval 0.18 to 0.47. The upper end of that interval is the gene's LOEUF score, 0.47, which puts it in group 2 of 6, group 1 being the genes least tolerant of losing a copy. Missense variants: 394 observed, 525.03 expected, observed/expected ratio (o/e) 0.75, 90% interval 0.69 to 0.82. Synonymous variants: 228 observed, 211.1 expected, observed/expected ratio (o/e) 1.08, 90% interval 0.97 to 1.21.
Homologues: Orthologues: dog ACOT7 (95% identical), chimpanzee ACOT7 (90% identical), pig ACOT7 (89% identical), guinea pig ACOT7 (87% identical), mouse Acot7 (85% identical), rat Acot7 (85% identical), macaque ACOT7 (81% identical), tropical clawed frog acot7 (74% identical), rabbit ACOT7 (67% identical), zebrafish acot7 (57% identical). Paralogues in human: ACOT12 (22% identical), ACOT11 (21% identical).
Diseases named in the same sentence as ACOT7 in open-access papers:
ACOT7 is named in the same sentence as 54 diseases in open-access papers, as found by Europe PMC text mining. Sharing a sentence is not in itself a finding about the gene and the disease. The quoted sentences say what the papers report.
asthma (6 papers, 2019 to 2024). "DNA methylation in CpGs annotated to the ZFPM1 (cg04983687, cg08940169) and ACOT7 (cg09249800, cg21220721, cg11699125) genes were also shown to be strongly associated in the asthma study and in our analysis focusing on ADEH+." (PMID 31443688, 2019). "Discovered DMRs annotated to genes implicated in allergy and asthma, Th2 activation and eosinophilia (EPX, IL4, IL13, PRG2, CLC and ZFMP1) and genes previously associated with asthma and IgE in an EWAS of blood (ACOT7, SLC25A25)." (PMID 35344303, 2022). "The role of methylations of ACOT7 gene in asthma has been reported by several genome-wide epigenomic studies on serum immunoglobin E (IgE) levels." (PMID 31932625, 2020). "Discovered DMRs annotated to genes implicated in allergic asthma, Th2 activation and eosinophilia (EPX, IL4, IL13) and genes previously associated with asthma and IgE in EWAS of blood (ACOT7, SLC25A25)." (PMID 31300640, 2019). "The PBMC data show that cytosolic acyl coenzyme A thioester hydrolase 7 (ACOT7) gene might act in concert with another candidate gene, Zinc Finger Protein 366 (ZNF366) gene, to jointly influence the risk of asthma." (PMID 31932625, 2020).
breast carcinoma (6 papers, 2005 to 2024). "ACOT7 expression increased in lung and breast carcinoma, and low levels of its expression were associated with better survival prognosis." (PMID 36230586, 2022). "Patients with low ACOT7 levels showed longer overall survival periods than breast cancer patients with high ACOT7 levels." (PMID 28518146, 2017).
lung carcinoma (6 papers, 2017 to 2025). "Moreover, a recent study showed that higher ACOT7 expression was associated with worse overall survival in breast and lung cancer patients." (PMID 33362855, 2020). "The expression of ARNTL2 and acyl-CoA thioesterase 7 (ACOT7) in lung cancer patients was analyzed based on TCGA database." (PMID 37003979, 2023). "ACOT7 has also been reported to be involved in cell cycle control as well as a target for therapies in breast and lung cancer." (PMID 36139682, 2022). "For instance, ACOT7 was observed to be highly expressed in lung cancer patients and was found to contribute to cancer development via promoting cell cycle progression." (PMID 33362855, 2020). "We also observed a synergistic effect of ACOT7 depletion in combination with either IR or doxorubicin on cell proliferation in breast and lung cancer cells." (PMID 28518146, 2017). "To assess the anti-tumor effect of ACOT7 depletion in combination with either IR or Doxo, we measured relative cell numbers and clonogenicity in ACOT7-depleted A549 human lung carcinoma cells." (PMID 28518146, 2017). "Analysis of the ACOT7 prognostic value revealed that low ACOT7 levels prolonged overall survival periods in breast and lung cancer patients." (PMID 28518146, 2017). "To further explore the role of ACOT7 in lung cancer, we performed cell function assays." (PMID 36139682, 2022). "Altogether, these results indicate that a decreased ACOT7 activity may be involved, at least in part, in prevention of human breast and lung cancer development via regulation of cell cycle progression." (PMID 28518146, 2017). "In addition, the antitumor effect of ACOT7 depletion is supported by analysis of the prognostic value and its higher expression level in lung cancer patient tissues than normal tissues." (PMID 28518146, 2017). "Together, our data suggest that a low level of ACOT7 may be involved, at least in part, in the prevention of human breast and lung cancer development via regulation of cell cycle progression." (PMID 28518146, 2017). "Furthermore, ACOT7 mRNA levels were higher in lung cancer patient tissues compared to normal tissues." (PMID 28518146, 2017). "However, the role of ACOT7 in pan-cancer and whether ACOT7 could be a prognostic indicator in lung cancer are still unknown." (PMID 36139682, 2022). "Furthermore, we assessed mRNA levels of ACOT7 in lung cancer patient tissues." (PMID 28518146, 2017). "In addition, ACOT7 expression was closely related to DSS, DFI, and PFI in several cancers, especially lung cancer." (PMID 36139682, 2022).
hepatocellular carcinoma (4 papers, 2022 to 2025). A malignant tumor that arises from hepatocytes. "On the contrary, KLF13 facilitated hepatocellular carcinoma progression via transcriptional activation of Acyl‐CoA thioesterase 7 to promote fatty acid metabolism." (PMID 41410190, 2025). "Activation of KLF13/ACOT7 axis supports the progression of hepatocellular carcinoma (HCC) through potentiation of oleic acid." (PMID 37003979, 2023).
type 2 diabetes (4 papers, 2015 to 2023). "We selected 14 disallowed genes for analysis based on their identification in 2 independent studies (C1qbp, Cd302, Cxcl12, Igfbp4, Ldha, Lmo4, Maf, Oat, Pdgfra, Slc16a1, and Smad3) and/or other criteria including up-regulation in type 2 diabetes (Acot7, Ldha, and Pdgfra)." (PMID 26038943, 2015).
liver cancer (3 papers, 2024 to 2025). An epithelial or non-epithelial malignant neoplasm that arises from the liver. "Overexpression of ACOT7 promotes the production of the monounsaturated fatty acid oleic acid, which enhances the proliferation and migration of liver cancer cells." (PMID 40823187, 2025). "We identified YWHAE as significantly associated with liver fibrosis, AVIL, FIS1, MUC1, ACOT7, CLUH, HNF4A, and TNFSF10 with liver cancer, and AVIL with liver disease-related mortality (FDR-adjusted P values < 0.05)." (PMID 38862964, 2024). "For instance, ACOT7 was proved to be upregulated in liver cancer cells infected with HBV." (PMID 38112462, 2024).
acute myeloid leukemia (2 papers, 2020 to 2023). Acute myeloid leukemia (AML) is a group of neoplasms arising from precursor cells committed to the myeloid cell-line differentiation. "In acute myeloid leukemia patients, higher expression of ACOT7 predicts the poorer prognosis of the patients." (PMID 37003979, 2023).
allergic asthma (2 papers, 2019 to 2022). A asthma with a basis in a pathological type I hypersensitivity reaction. "The replication external cohort for allergic asthma confirmed 61% differentially methylated CpGs (58 CpGs), including several sites annotated to the ACOT7, ZFPM1, PRG2, EPX and EVL genes." (PMID 35344303, 2022). "Of note, multiple DMRs (EPX, ACOT7 and SORCS2 genes) were overlapping across phenotypes like FeNO, allergic asthma, environmental IgE sensitization, and total IgE." (PMID 35344303, 2022). "In addition, multiple DMRs with five or more CpGs (EPX (eosinophil peroxidase), ACOT7, SORCS2 genes) were overlapping across phenotypes like FeNO, allergic asthma, environmental IgE sensitization, and total IgE." (PMID 31300640, 2019).
colorectal cancer (2 papers, 2025). A primary or metastatic malignant neoplasm that affects the colon or rectum. "In colorectal cancer, six genes were positively correlated: ANLN, ACOT7, OSBPL3, SEC61G, DDX56, and TRIM10." (PMID 40765570, 2025).
diabetes (2 papers, 2023 to 2025). "Here, increasing Acot7 and Fabp5 in β-cells correlates with a normal → diabetic shift, consistent with their known overexpression in diabetes." (PMID 41465115, 2025).
amyloid (1 paper, 2024). "This suggests that ACOT7 might have a significant involvement in amyloid pathogenesis of AD." (PMID 39026992, 2024).
cognitive decline (1 paper, 2024). "The correlation analysis between ACOT7 levels and cognitive decline was also performed to determine whether higher ACOT7 expression was associated with more severe disease or not." (PMID 39026992, 2024).
colon adenocarcinoma (1 paper, 2024). "APOA2 is known to be involved in high density lipoprotein (HDL) metabolism, while acyl-CoA thioesterase 7 (ACOT7) is important in unsaturated fatty acid biosynthesis which is involved in the initiation and progression of colon adenocarcinoma (COAD)." (PMID 39494346, 2024).
esophagogastric adenocarcinoma (1 paper, 2022). "The deep deletion and amplification of the ACOT7 gene represent one of the critical factors leading to mutations, especially in ovarian epithelial tumors, esophagogastric adenocarcinoma, PAAD, SARC, and ESCA." (PMID 36139682, 2022).
Glucose intolerance (1 paper, 2016). Glucose intolerance (GI) can be defined as dysglycemia that comprises both prediabetes and diabetes. "We have also recently demonstrated the importance of the silencing of another member of this family, the Acyl-CoA thioesterase 7 (Acot7) which β-cell specific overexpression lead to glucose intolerance and impaired insulin secretion in response to glucose." (PMID 28123396, 2016).
Insulin resistance (1 paper, 2015). Increased resistance towards insulin, that is, diminished effectiveness of insulin in reducing blood glucose levels. "Doubling cytosolic acyl-CoA thioesterase activity failed to protect mice from diet-induced obesity, fatty liver or insulin resistance, however, overexpression of Acot7 in adipocytes rendered mice cold intolerant." (PMID 25760036, 2015).
invasive breast carcinoma (1 paper, 2020). A carcinoma that infiltrates the breast parenchyma. "The gene expressions of ACOT7, STAT1, TYMP, and VOPP1 were significantly increased in invasive breast carcinoma, while the gene expressions of ACTG2, CNN1, CDC14B, NFIB, RCN1, and TRIM2 were dramatically downregulated in BRCA." (PMID 31986487, 2020).
lung adenocarcinoma (1 paper, 2022). A carcinoma that arises from the lung and is characterized by the presence of malignant glandular epithelial cells. "The function of ACOT7 in pan-cancer and its capacity as a prognostic indicator in lung adenocarcinoma (LUAD) remains unknown." (PMID 36139682, 2022). "ACOT7 is a novel oncogene and therapeutic target for lung adenocarcinoma." (PMID 36139682, 2022).
malignant melanoma (1 paper, 2025). "Microarray analysis related to malignant melanoma also reported that tumor progression was related to the high expression of ACOT7." (PMID 40823187, 2025).
mastitis (1 paper, 2024). Inflammation of breast tissue during lactation or postpartum due to an obstructed duct or infection. "This study offers novel insights by identifying ACOT7 as a key enzyme that connects fatty acid metabolism to inflammation, thereby addressing a significant gap in the literature concerning its role in dairy cows with mastitis." (PMID 39684757, 2024).
neuroblastoma (1 paper, 2024). Neuroblastoma (NB) is the most common solid, extracranial childhood tumor. "In the present study, RNA interference was employed to investigate the impact of ACOT7 knockdown on APP metabolism in neuroblastoma SK-N-SH APPwt cells." (PMID 39026992, 2024).
Obesity (1 paper, 2015). Accumulation of substantial excess body fat. "The loss of Acot7, Acot11/Them1, Acot13/Them2, and Acot15/Them5 result in phenotypes ranging from increased neurodegeneration to altered susceptibility to high-fat diet induced obesity, fatty liver, and insulin resistance through unknown mechanisms that unexpectedly altered whole body metabolism." (PMID 25760036, 2015).
retinoblastoma (1 paper, 2015). A malignant tumor that originates in the nuclear layer of the retina. "The capacity for miR-200a to repress ACOT7 in retinoblastoma cells suggests a novel contributory role of ACOTs in retinoblastoma progression." (PMID 26379276, 2015). "From within this cohort, we observed that ACOT7 and DLL3 are positively expressed in each retinoblastoma tumor evaluated, in addition to adjacent retina." (PMID 26379276, 2015). "Expression of ACOT7 and DLL3 was observed in a majority of retinoblastomas available for analysis, and were also expressed in retinal tissues (n = 5)." (PMID 26379276, 2015). "To establish clinical relevance of ACOT7 and DLL3, we performed immunohistochemistry on four human pediatric retinoblastomas representing individual patients." (PMID 26379276, 2015). "From these observations, it is plausible that as retinoblastoma progresses, overexpression of DLL3 and ACOT7 could be characteristic features." (PMID 26379276, 2015). "Among the most downregulated mRNAs in Y79 cells, ACOT7 and DLL3 represent novel therapeutic targets for future retinoblastoma studies, which we found to be expressed in primary retinoblastomas and retinas, and overexpressed in retinoblastoma cell lines as compared to normal retinas." (PMID 26379276, 2015). "Furthermore, our work is the first to demonstrate that overexpression of miRNA-31 and/or miR-200a results in differential gene expression patterns of ACOT7, DLL3, PPP6C, and STK40 between two phenotypically different retinoblastoma cell lines." (PMID 26379276, 2015).
tumor (16 papers, 2015 to 2026). "ACOT7 mRNA expression was associated with more advanced clinicopathological parameters, including lymph node metastasis and tumor size." (PMID 38770369, 2024). "Our findings also suggested that ACOT7 was significantly associated with genes encoding tumor immunity factors." (PMID 36139682, 2022). "The heatmaps of immune-related gene expression patterns revealed that these genes were closely associated with ACOT7 expression in most tumor types (p < 0.05)." (PMID 36139682, 2022). "ACOT7 was tightly associated with the tumor microenvironment." (PMID 36139682, 2022). "More importantly, the study pointed out that the small molecule inhibitor fludarabine can target NAT10 and inhibit the acetylation modification of ACOT7 mRNA, inhibiting the acetylation modification of ACOT7 mRNA and effectively preventing tumor development." (PMID 40539051, 2025). "Combined with the clinicopathological characteristics, we found that a high protein level of ACOT7 was correlated with advanced tumor size, lymph node metastasis, and Ki-67 index." (PMID 38770369, 2024). "We found that the mRNA levels of ACOT7 in BC tissues were significantly higher than that in adjacent non-tumor tissues." (PMID 38770369, 2024). "Tumor xenografts of the LV-ACOT7 group displayed elevated expression of ACOT7 protein level and a significant increase in the abundance of Ki-67 positive cells." (PMID 38770369, 2024). "ACOT7 expression was related to the tumor node metastasis (TNM) stage in six cancers: HNS, KIRC, KIRP, LIHC, LUAD, and THCA." (PMID 36139682, 2022). "Furthermore, ACOT7 transcriptional levels showed a significant correlation with the degree of tumor immune infiltration." (PMID 41822488, 2026). "Furthermore, a protein-protein interaction (PPI) network of ACOT7 was constructed by GeneMANIA, and the correlation between ACOT7 expression and the level of tumor immune infiltration was explored via the TIMER database." (PMID 41822488, 2026). "As shown, ACOT7 depletion induced tumor sensitivity either to IR or Doxo." (PMID 28518146, 2017). "ACOT7 inhibition may be a promising anti-tumor strategy for BC cells with high ACOT7 expression." (PMID 38770369, 2024). "Six genes—ARHGEF19, CORO1A, ACOT7, ZC3H18, SLC5A5, and ZFAS1—showed statistically significant differential expression between tumor and normal tissues (P < 0.05)." (PMID 40070828, 2025). "In accordance with the results of mass spectrometric profiling of tumor tissues, these proteins were shown to be mostly increased in comparison with control, while reaching statistical significance in certain instances (AP + AG and 5-FU vs. Control for APOA2; 5-FU vs. Control for ACOT7)." (PMID 39494346, 2024).